ICA1L (islet cell autoantigen 1 like)
Synonyms: ALS2CR14; ALS2CR15
Tractability: PROTAC: its protein half-life has been measured.
Gene: Protein-coding gene on chromosome 2 (202,773,150 to 202,872,061, reverse strand). Ensembl gene ENSG00000163596.
Subcellular location (Human Protein Atlas): Mitochondria
Gene Ontology:
Molecular function: protein binding; membrane curvature sensor activity; protein domain specific binding
Biological process: membrane bending; regulation of secretion
Cellular component: secretory granule membrane; acrosomal vesicle; cytoplasm; endomembrane system
Genetic constraint (gnomAD): Loss-of-function variants: 14 observed, 25.52 expected, observed/expected ratio (o/e) 0.55, 90% interval 0.36 to 0.86. The synonymous counts are far from expectation, so gnomAD's model fits this gene poorly and the ratio says little. Missense variants: 271 observed, 325.06 expected, observed/expected ratio (o/e) 0.83, 90% interval 0.75 to 0.92. Synonymous variants: 88 observed, 117.41 expected, observed/expected ratio (o/e) 0.75, 90% interval 0.63 to 0.89.
Homologues: Orthologues: macaque ICA1L (97% identical), chimpanzee ICA1L (94% identical), dog ICA1L (88% identical), pig ICA1L (85% identical), rat Ica1l (75% identical), mouse Ica1l (73% identical), guinea pig ICA1L (68% identical), zebrafish ical1 (55% identical), Drosophila melanogaster ICA69 (31% identical), Caenorhabditis elegans ric-19 (27% identical). Paralogues in human: ICA1 (50% identical).
Diseases named in the same sentence as ICA1L in open-access papers:
ICA1L is named in the same sentence as 20 diseases in open-access papers, as found by Europe PMC text mining. Sharing a sentence is not in itself a finding about the gene and the disease. The quoted sentences say what the papers report.
Stroke (6 papers, 2022 to 2023). Sudden impairment of blood flow to a part of the brain due to occlusion or rupture of an artery to the brain. "Previous research has established a correlation between elevated ICA1L expression and a decreased risk of Alzheimer's disease, stroke, and small vessel strokes." (PMID 37592229, 2023). "Using PWAS, TWAS, MR and Bayesian colocalization analyses, ICA1L and NBEAL1 were proved to be causal for stroke in brains." (PMID 35449099, 2022). "Of them, 24 analyses performed colocalization analyses with the outcome of interest, of which two found evidence for colocalization between the risk factor and the outcome (Islet cell autoantigen 1-like protein (ICA1L) for stroke and neurokinin 3 receptor (NK3R) for CHD)." (PMID 37804188, 2023). "Since stroke shows a marked sex bias with men having greater incidence of stroke, potential differential expression of ICA1L between male and female may account for this divarication." (PMID 35449099, 2022). "SNP rs116426890 is intronic to ABI2 and is linked to the expression of CARF, ICA1L, FAM117B, and NBEAL1 which are associated with both white matter hyperintensities and fractional anisotropy, predictors of cerebral small vessel disease which is involved in strokes and vascular dementia." (PMID 36684006, 2022). "Genes ICA1L and NBEAL1 were mapped by the same locus (index SNP: rs114123510), and both are related to cholesterol metabolism, in which dysregulation promotes the pathology of atherosclerosis, MI, and strokes." (PMID 35250867, 2022). "Furthermore, we identified ICA1L, CAND2, and ALDH2 from comprehensive analyses, including non-lacunar stroke brain PWAS and colocalization, and ICA1L was supported at the brain transcriptional level." (PMID 35733147, 2022).
small vessel stroke (4 papers, 2022 to 2025). "Our integrative analysis revealed that ICA1L was associated with small-vessel stroke (SVS), according to robust evidence at both protein and transcriptional levels based on brain-derived data." (PMID 35449099, 2022). "Increased ICA1L expression is also associated with a lower risk of AD and small vessel strokes (SVSs), the acute outcomes of cerebral SVD, which may lead to VaD." (PMID 40141087, 2025). "In conclusion, this integrative analysis identified ICA1L and NBEAL1, whose expression and protein abundances are associated with the risk of small-vessel stroke." (PMID 35449099, 2022).
Alzheimer disease (3 papers, 2023). A progressive, neurodegenerative disease characterized by loss of function and death of nerve cells in several areas of the brain leading to loss of cognitive function such as memory and language. "At chr2q33.2, also associated with WMH, SVS, Alzheimer’s disease and caudate volume, BG-PVS was associated with higher expression of ICA1L in brain tissues and of NBEAL1 in vascular tissues, similar to TWAS of WMH and SVS5,22." (PMID 37069360, 2023). "Previous proteome-wide association studies have discovered the brain protein abundance of ICA1L to affect cerebral small vessel diseases and Alzheimer’s disease." (PMID 37306871, 2023).
cerebral small vessel disease (3 papers, 2022 to 2023). Cerebral small vessel disease is the term currently used to pathological processes that affect the brain parenchymal circulation (arterioles, capillaries, and veins). "Of the identified genes, ICA1L was previously discovered in a GWAS of cerebral small vessel disease and its genetically elevated expression was associated with lacunar stroke in TWAS." (PMID 35449099, 2022).
coronary artery disease (2 papers, 2023 to 2025). "Furthermore, ICA1L has been identified as a shared risk gene between migraine and coronary artery disease (CAD)." (PMID 37592229, 2023).
migraine (2 papers, 2023). "Findings from cell-type specificity analysis in the brain have identified enrichment in the ICA1L expression in glutamatergic excitatory neurons, while malfunctioning of the glutamatergic system may cause symptoms of migraine." (PMID 37306871, 2023). "To date, little is known regarding the exact biological functions of TREX1 and ICA1L in migraine and kidney function, and future functional studies are worth revealing their roles." (PMID 37306871, 2023). "While, four of these (ICA1L, TREX1, STAT6, and UFL1) have been previously reported in association with migraine." (PMID 37592229, 2023). "Through our analysis of two different brain proteomes using PWAS and TWAS of brain and vascular transcriptomes, we identified three potential causal genes for migraine (STAT6, ICA1L, and TREX1)." (PMID 37592229, 2023). "Therefore, it can be postulated that ICA1L plays a convergent role in the initiation and progression of migraine, AD, and SVD." (PMID 37592229, 2023). "In addition, ICA1L, shared by migraine and UACR, and expressed in the brain, artery, pancreas, and skin tissues, encodes islet cell autoantigen 1-like (ICA1L) protein that is involved in protein domain specific binding activity and regulation of transport." (PMID 37306871, 2023). "Five genes, including ICA1L, TREX1, STAT6, UFL1, and B3GNT8, showed significant correlation with migraine in both the proteome and transcriptome." (PMID 37592229, 2023). "Furthermore, nine significant tissue–gene pairs were found for migraine and UACR using GTEx tissues, including four genes (NBEAL1, FAM117B, ICA1L) mainly expressed in tissues of the nervous and cardiovascular system." (PMID 37306871, 2023).
cervical cancer (1 paper, 2024). A primary or metastatic malignant neoplasm involving the cervix. "While ICA1L gene has previously been linked to neoplasms exhibiting incomplete smooth muscle differentiation, this gene’s role in cervical cancer has not been described." (PMID 38540371, 2024).
Cognitive impairment (1 paper, 2023). Abnormal cognition is characterized by deficits in thinking, reasoning, or remembering. "They presented the role of neural cell adhesion molecule 2 (NCAM2) and ICA1L (AD gene marker) in the process leading to cognitive impairment, which may be a potential target for AD intervention." (PMID 36845421, 2023).
COVID-19 (1 paper, 2022). A disease caused by infection with severe acute respiratory syndrome coronavirus 2. "Meanwhile, we also observed some unique changes in COVID-19 brains such as ICA1L, whose protein abundance was identified as significantly associated with AD in blood and brain studies." (PMID 36211330, 2022).
dementia (1 paper, 2025). Loss of intellectual abilities interfering with an individual's social and occupational functions. "Nevertheless, future research could validate ICA1L as a biomarker through longitudinal studies assessing its levels in cerebrospinal fluid and blood, investigating its ability to cross the blood–brain barrier, and characterizing how it correlates with dementia-related outcomes." (PMID 40141087, 2025).
ICA1L also shares sentences with these, for which no sentence is quoted: neoplasm (2 papers); amyotrophic lateral sclerosis (1); angina pectoris (1); atherosclerosis (1); breast tumor (1); Globozoospermia (1); ischemic stroke (1); myocardial infarction (1); neurodegenerative disease (1); vascular dementia (1).